MGMT (O-6-methylguanine-DNA methyltransferase)
Diseases named in the same sentence as MGMT in open-access papers (continued):
Sharing a sentence is not in itself a finding about the gene and the disease.
lung carcinoma (continued). "Based on previous studies and our investigation, we believed that the methylation of 6 tumor suppressor genes (FHIT, p16, MGMT, RASSF1A, APC, and DAPK) was associated with the prognosis of lung cancer patients." (PMID 34257703, 2021). "Methylated FHIT, MGMT, p16, and RASSF1A are underlying superior biomarkers, which can be used for lung cancer screening and auxiliary detection." (PMID 34257703, 2021). "Compared with primary lung cancer, MGMT expression was enhanced in brain metastases, and MGMT expression in brain metastasis was significantly associated with better survival." (PMID 31889956, 2019). "We also performed cell viability and IC50 values analysis to evaluate the regulation effect of Trps1 and MGMT on the drug‐resistant ability of lung cancer cells." (PMID 29601666, 2018). "Taken together, we consider that upregulation of Trps1 induces MGMT transcription contributing to the formation of MDR in lung cancer cells." (PMID 29601666, 2018). "In the present study, we occasionally found that Trps1 and MGMT expressions both increased in cisplatin‐resistant lung cancer cells (H446/CDDP)." (PMID 29601666, 2018). "Our results demonstrated that Trps1 and MGMT expression both increased in drug‐resistant lung cancer cell line (H446/CDDP)." (PMID 29601666, 2018). "Taken together, our data verify that Trps1 gene is an up mediator of MGMT gene, and Trps1 enhanced antidrug abilities of lung cancer cells are at less partially contributed by MGMT." (PMID 29601666, 2018). "Multidrug resistance (MDR) often leads to chemotherapy failure of lung cancer and has been linking to the cellular expression of several DNA transcription‐ and repair‐related genes such as Trps1 and MGMT." (PMID 29601666, 2018). "Promoter hypermethylation of MGMT and p16 gene in peripheral blood has been reported in primary lung cancer and nonsmall cell lung cancer patients." (PMID 24991542, 2014). "Specifically using MSP, they looked at methylation of CDKN2A, MGMT, DAPK and GSTP1, genes whose aberrant methylation profiles have already been shown to associate with lung cancer risk or diagnosis." (PMID 23870182, 2013). "Methylation events in plasma, specifically in CDKN2A, MGMT and RASSF1A, as well as in peripheral blood leukocytes and lymphocytes, are promising less invasive sites for assessing lung cancer risk through measuring DNA methylation differences." (PMID 23870182, 2013). "The frequencies of tumors with a homogeneous MGMT staining and an unmethylated promoter ranged between 100% (7 of 7 clear cell renal cell carcinomas) and 86% (12 of 14 lung carcinomas)." (PMID 19274096, 2009). "Moreover, the role of MGMT in DNA repair and its oncogenic implications due to promoter methylation in lung cancer are well-established." (PMID 39661479, 2025). "This includes hypermethylation-mediated silencing of mutL homolog 1 (MLH1), ataxia-telangiectasia mutated (ATM), and O-6-methylguanine-DNA methyltransferase (MGMT), which compromises DNA damage response and contributes to chemo-resistance characteristic of dormant lung cancer cells." (PMID 41303477, 2025). "Furthermore, NCI677397‐treated T98G cells, which are TMZ‐resistant GBM cells with high MGMT expression, also markedly increased autophagy, and a similar effect was observed in lung cancer cells, namely, A549 and Taxol‐resistant A549 (A549‐T24) cells." (PMID 38140768, 2024). "More research is required to determine whether MGMT‐expression is a signal for early lung cancer detection." (PMID 37901797, 2023). "Additionally, compared with healthy controls, patients with lung cancer had lower levels of MGMT protein expression in their bronchial epithelium, indicating a possible link between MGMT expression and the risk of developing lung cancer." (PMID 37901797, 2023).
lung carcinoma (continued). "Conversely, promotion of the hypermethylation of the O-6-methylguanine DNA methyltransferase (MGMT) gene is a distinctive feature of lung cancer, while in IPF fibroblasts, MGMT is hypomethylated, demonstrating, however, the existence of disease-specific methylation patterns." (PMID 33809111, 2021). "Moreover, tumor suppressor genes such as p16, APC, and MGMT were substantiated to be hypermethylated in lung cancer tissue." (PMID 34257703, 2021). "The results revealed a much higher odds ratio in cancer tissue than that in normal lung tissue and plasma A study on the expression of MGMT promoter methylation in BMs from solid tumors showed that the incidence rate of promoter methylation of lung cancer was the highest (46.5%)." (PMID 33371090, 2020). "MGMT promoter hypermethylation is a common event in lung cancer patients." (PMID 31889956, 2019). "To elucidate the regulating effect of Trps1 on MGMT expression in lung cancer, we detected the functional interactions between Trps1 and MGMT in a typical small cell lung cancer cell line (H446) by both downregulation and upregulation of Trps1 or MGMT, respectively." (PMID 29601666, 2018). "In addition, the methylation of FAM19A4, FHIT, and MGMT were reported to play important roles in the occurrence and deterioration of lung cancer." (PMID 28644424, 2017). "Work on identifying CDKN2A, as well as MGMT, as a measure of cancer risk and diagnosis was expanded in a 21-patient study of matched sputum and squamous cell carcinoma (SCC) samples as well as sputum samples from 32 patients evaluated for possible lung cancer." (PMID 23870182, 2013). "MGMT promoter methylation is a common event in primary human neoplasms including lung cancer." (PMID 24212786, 2011). "In addition, only a relative small study has examined the relationship between polymorphisms in XRCC1, GSTM1, GSTP1, NQO1, and MPO and aberrant methylation of p16, RARβ and MGMT in lung cancer." (PMID 20704749, 2010). "A low protein expression of MGMT was found in the bronchial epithelium of patients with lung cancer as compared to healthy controls, suggesting that there is a negative correlation between MGMT expression and lung cancer risk." (PMID 34970479, 2021). "Therefore, given the transcriptional activity of Trps1, whether Trps1 regulates MGMT expression is quite a significant question for the development of MDR in lung cancer." (PMID 29601666, 2018). "Aberrant DNA methylation affecting the O6-methylguanine-DNA methyltransferases (MGMT) gene has been revealed in HPV-negative OPSCC, but also in lung cancer, suggesting the loss of the repair function of MGMT may reduce the ability of cells to repair DNA damage in smoking-induced tumors." (PMID 29209433, 2017). "The highest prevalence of MGMT promoter methylation was found in male nonsmokers followed by male smokers and female nonsmokers, which does not support the hypothesis that the lung cancer risk is higher in women." (PMID 24212786, 2011). "The “new” autoantibodies in our panel target TAAs like DCTPP1, GIMAP4, WWP2, MGMT, KCMF1, and GDA, which have demonstrated links to lung cancer pathogenesis." (PMID 39661479, 2025). "Epigenetic Indicators for Early Detection of Lung Cancer: Hypermethylation of genes like RARB, CDKN2A, and MGMT have emerged as promising biomarkers for lung cancer early detection, prognosis, and prediction of therapeutic response." (PMID 39982247, 2025). "Another research also reported that the rate of MGMT promoter methylation in the plasma and bronchoalveolar lavage fluid (BLAF) of lung cancer patients is significantly higher than that of healthy individuals." (PMID 40666096, 2025).
lung carcinoma (continued). "Two of them, cyclin-dependent kinase inhibitor 2A (CDKN2A), which encodes the tumor suppressor p16, and O-6-methylguanine-DNA methyltransferase (MGMT), are methylation targets shared by COPD and lung cancer." (PMID 36765688, 2023). "Tobacco smoking has been shown to be associated with an increased DNAm of specific genes in somatic analyses of lung cancers (e.g., p16, APC, MGMT, ANK1, MTHFR)." (PMID 35205708, 2022). "This study identified FHIT, MGMT, P16, RASSF1A, APC, and DAPK as methylation markers of lung cancer through literature review and previous studies." (PMID 34257703, 2021). "The methylation frequencies of 6 genes (FHIT, p16, MGMT, RASSF1A, APC, DAPK) in lung cancer patients, the basic clinical information, and tumor marker levels of these patients were analyzed." (PMID 34257703, 2021). "In conclusion, despite these limitations, our meta-analysis advocates that methylated SOX17, CDO1, ZFP42, TAC1, FAM19A4, FHIT, MGMT, p16, and RASSF1A are useful biomarkers in the screening and auxiliary detection of lung cancer." (PMID 28644424, 2017). "Abundant evidence manifests that a variety of well-known DNA methylations can be used as a promising biomarker for the early diagnosis of lung cancer, such as p16, RASSF1A, APC, MGMT, DAPK and RARβ." (PMID 28644424, 2017). "Numerous studies showed that in lung cancer, the hypermethylation modification of the CpG island in promoter regions of tumor suppressor genes, such as FHIT, p16, MGMT, RASSF1A, APC, and DAPK, leads to the occurrence of lung cancer and poor prognosis in lung cancer patients." (PMID 34257703, 2021). "In our previous study, we have occasionally found a positive correlation between MGMT and Trps1 in lung cancer cells (data not show)." (PMID 29601666, 2018). "Therefore, to fully elucidate the regulation mechanism of MGMT expression is important to reveal and reversal the MDR formation for lung cancer cells." (PMID 29601666, 2018). "To answer the question as to whether MGMT could affect the potency of EG22, we tested its potency in a panel of cells with known MGMT status, including an isogenic pair of human lung cancer cell line, A427 and A427 MGMT cell lines." (PMID 28800752, 2017). "Therefore, we advocate that methylated SOX17, CDO1, ZFP42, TAC1, FAM19A4, FHIT, MGMT, p16, and RASSF1A are useful in the screening and auxiliary detection of lung cancer." (PMID 28644424, 2017). "Loss- and gain-of-function experiments in human bronchial epithelial and lung carcinoma cell lines revealed that Ascl1, MMP-7 and MGMT are able to protect cells from the tobacco-specific nitrosamine NNK-induced DNA damage and the alkylating agent cisplatin-induced apoptosis." (PMID 23300791, 2012). "The DNA repair gene, MGMT, frequently inactivated in brain, colorectal, lung, and lymphomas, and the potential metastasis inhibitor DAP-kinase gene altered in lymphomas, leukaemias, and lung cancer, were also reported with aberrant methylation." (PMID 17968429, 2007). "Several combinations of differentially methylated gene promoter regions were found to be more effective than single gene promoters (RASSF1A/RARB2, SHOX2/PTGER4, RTEL1/PCDHGB6, HOXD10/PAX9/PTPRN2/STAG3, APC/AIM1/CDH1/DCC/MGMT/RASSF1A) in distinguishing lung cancer patients from noncancerous controls." (PMID 36765815, 2023). "Furthermore, MGMT methylation is seen in COPD and lung cancers due to chronic tobacco abuse." (PMID 33917711, 2021). "However, MGMT did not allow a clear discrimination of the tumor type and hence might be limited as a biomarker in lung cancer." (PMID 29851970, 2018).
lung carcinoma (continued). "RARβ, CDKN2A, DAPK, RASSF1A and MGMT were examined, and the analysis showed that a patient having methylation of just one gene had an odds ratio of 5.08, meaning they were approximately five times likely to have lung cancer than patients without any methylated genes." (PMID 23870182, 2013). "The most frequently analyzed genes like p16, DAPK, APC, RASSF1A, MGMT, FHIT, RARß and GSTP1 were applied as a means of detecting lung cancer or as prognostic factor but none of them had been used for therapy monitoring." (PMID 25675432, 2015). "By looking at the sputum of lung cancer-surviving smokers, cancer-free smokers and never smokers, then adjusting for age and smoking duration, MGMT, RASSF1A, DAPK and PAX5α were also identified as being significantly differently methylated in the lung cancer survivors." (PMID 23870182, 2013).
breast carcinoma (56 papers, 2005 to 2025). "Constitutional BRCA1 promoter methylation and MGMT promoter methylation have been shown to be associated with an increased risk of ovarian cancer and breast cancer." (PMID 38542081, 2024). "Prior studies have shown a correlation between MGMT promoter methylation and susceptibility to breast cancer, which is somewhat associated with older age." (PMID 38542081, 2024). "In the present study, MGMT expression was also found to be significantly associated with ER positivity in breast cancer." (PMID 33033516, 2020). "In the present study, it was found that MGMT expression was significantly associated with ER positivity in breast cancer." (PMID 33033516, 2020). "Increased MGMT protein activity is associated with HR-positive breast cancer subtypes, while lower expression reduces MGMT protein activity." (PMID 32841306, 2020). "We have also reported that inhibition of MGMT in an in vitro breast cancer model is associated with CDK4 inhibition and enhances palbociclib and abemaciclib effect." (PMID 30038716, 2018). "There was a statistically significant association between the MGMT promoter methylation and late-onset breast cancers." (PMID 30049288, 2018). "In recent years, several researchers have reported loss of MGMT in breast cancer thereby implicating defective alkylation repair in breast cancer development." (PMID 28679371, 2017). "The association between MGMT expression and the clinical outcome was examined to explore the possibility of MGMT expression as a predictive marker in patients with breast cancer treated with CPM-containing chemotherapy." (PMID 24932232, 2014). "In summary, MGMT expression was significantly associated with ER positivity in breast cancer." (PMID 33033516, 2020). "Similarly, in breast cancer, loss of MGMT was recently linked to temozolomide sensitivity in a pre-clinical study." (PMID 28679371, 2017). "Loss of MGMT expression has been associated with aggressive tumour behaviour and progression in several types of neoplasia, including esophageal, hepatocellular, lung, gastric and breast carcinomas." (PMID 28499365, 2017). "In a previous study, MGMT methylation has been associated with the age of breast cancer patients." (PMID 26370119, 2015). "In this study, we aimed to determine the roles of constitutional BRCA1 promoter methylation and MGMT promoter methylation in the incidence of breast cancer in Saudi women." (PMID 38542081, 2024). "Our data indicate that BRCA1 and MGMT epimutations significantly contribute to the development of breast cancer and ovarian cancer in Saudi cancer patients." (PMID 38542081, 2024). "We previously established that constitutional MGMT promoter methylation is highly related to both ovarian cancer and late-onset breast cancer in a study including 67 breast cancer patients and 82 ovarian cancer patients." (PMID 38542081, 2024). "Materials and methods: The immunohistochemistry assay and a series of public databases were utilized to determine the relevance between MGMT expression and clinicopathological characteristics, as well as survival outcomes in patients with breast cancer." (PMID 33033516, 2020). "In MCF7 breast cancer cells, the steady-state levels of MGMT are upregulated by about four-fold after Nrf2 levels were elevated using an expression vector." (PMID 32075134, 2020). "To further investigate the potential function of MGMT in breast cancer, we performed proliferation and colony formation assays in MCF-7 and MDA-MB-231 cells." (PMID 33033516, 2020). "Down-regulation of MGMT expression enhanced the proliferative and invasive capacities of breast cancer cells through PTEN/AKT pathway." (PMID 33033516, 2020). "Survival analysis demonstrated that MGMT positive expression was associated with a better DFS and OS in patients with breast cancer." (PMID 33033516, 2020).